LINC00661 (long independently transcribed non-coding RNA 661)
Gene: Long non-coding RNA gene on chromosome 19 (16,015,287 to 16,027,462, forward strand). Ensembl gene ENSG00000205396.
Diseases named in the same sentence as LINC00661 in open-access papers:
LINC00661 is named in the same sentence as 2 diseases in open-access papers, as found by Europe PMC text mining. Sharing a sentence is not in itself a finding about the gene and the disease. The quoted sentences say what the papers report.
tumor (1 paper, 2021). "In our study,the expressions of CHRM3.AS2, MIR205HG, and LINC00661 were significantly increased in tumor tissues of CCA patients, further verifying the prognostic prediction value of the established signatures for CCA." (PMID 34926294, 2021). "The expressions of CHRM3.AS2, MIR205HG, and LINC00661 from the TCGA and GEO databases were remarkably upregulated in tumor tissues compared with those in normal tissues." (PMID 34926294, 2021).
LINC00661 also shares sentences with these, for which no sentence is quoted: basal cell carcinoma (1 paper).